CCND1 (cyclin D1)
Diseases named in the same sentence as CCND1 in open-access papers (continued):
Sharing a sentence is not in itself a finding about the gene and the disease.
tumor (continued). "The expression levels of cyclin D1 were defined as overexpression when more than 10% of tumor cells displayed nuclear staining with moderate to strong intensity." (PMID 22336657, 2012). "The delay in time to tumor corresponded with a significant reduction in cyclin D1 protein expression in the tumors." (PMID 23320178, 2012). "Using a Cox regression analysis, CCND1 amplification appeared to be the only single gene which was a predictor of survival aside from grade, mitotic count, and tumor size (p = 0.015; hazard ratio 3.0)." (PMID 22527098, 2012). "PK-PD studies on the tumor samples clearly demonstrated down regulation of protein levels for cyclin D1, pRbSer780 along with antiapoptotic proteins viz." (PMID 23075291, 2012). "Cytoplasmic cyclin D1 expression was inversely correlated to tumour size (all patients; P = 0.01) and nodal status (P = 0.031), and was positively correlated to proliferation (P = 0.021)." (PMID 22475046, 2012). "The Wnt/β-catenin signaling pathway has been shown to play an important role in the regulation of cyclin D1, which plays a crucial role in cell-cycle regulation and progression in a variety of tumor cells." (PMID 22701509, 2012). "NF-κB can also stimulate tumor proliferation through inducing certain oncogenes such as cyclin D1 and c-MYC." (PMID 22952718, 2012). "When β-catenin is translocated to the nucleus, it activates target genes, such as cyclin D1 and c-myc, and promotes the growth of tumor cells." (PMID 23013480, 2012). "In contrast to Sox7, the upregulated β-catenin was correlated with high-grade tumor (P = 0.045), and two Wnt/β-catenin specific downstream targets; Cyclin D1 (P < 0.001) and FGF9 (P = 0.003)." (PMID 23295859, 2012). "Taken together, the attenuation or prevention of tumor growth because of targeting MCT-1 again closely connects to the inhibitory effect on Shc-ERK-Cyclin D1 cascade." (PMID 23211466, 2012). "miR-16 and miR-15 act as tumor suppressors and control cell cycle transition by targeting cyclin D1 and cyclin E." (PMID 22260523, 2012). "Surprisingly, a greater fraction of cyclin D1-positive nuclei was associated with longer TTR (HR = 0.60; 95% CI, 0.39 to 0.92; P = 0.03) when adjusted for the effects of tumour size, nodal status, grade and Ki67 expression." (PMID 22475046, 2012). "Various studies have described the oncogenic capacity of cyclin D1 in vitro, and overexpression in vivo results in tumour formation." (PMID 22475046, 2012). "In several studies, over-expression (Cyclin D1, NF-κB, PCNA) or loss of expression (Bcl-2) of these markers have been found to correlate with more aggressive tumor growth in CRC." (PMID 23133595, 2012). "Inhibiting the expression of cyclin D1 will retard the cell cycle in G1 phase from entering into S phase, and therefore, significantly decrease tumor cell proliferation." (PMID 22911830, 2012). "PRb was abnormal in 168 (86%), p16 in 98 (49%), p21 in 151 (75%), and cyclin D1 in 143 (71%) of the tumours." (PMID 23304558, 2012). "Apart from the role as a prognostic marker, cyclin D1 has been proposed as a predictive factor for tamoxifen response, as illustrated by poor clinical outcome in patients with ER-positive tumours with high cyclin D1 expression treated with tamoxifen." (PMID 22475046, 2012). "The observed positive correlation between nuclear cyclin D1 expression and tumour grade and proliferation suggests a link between cyclin D1 and aggressive disease." (PMID 22475046, 2012).
tumor (continued). "We observed that the expression level of p21 was markedly up-regulated, while cyclin D1 down-regulated after tumour cells were treated with cyclopamine." (PMID 22799764, 2012). "Many of its target genes, such as cyclin D1, c-myc, Bcl-2, survivin and p21cip1 have been shown to control tumor cell survival and proliferation." (PMID 22723956, 2012). "STAT3 relevance in oncogenesis/tumor progression is widely acknowledged, via regulating apoptosis-related genes (Bcl-XL, Mcl-1 and Survivin), proliferation- (c-myc and cyclin D1) and invasion-promoting genes (VEGF, MMP-9)." (PMID 23028842, 2012). "The mice started to develop mammary gland tumors at 400 days and the tumor-free incidence was 40% in MMTV-cyclin D1." (PMID 22538871, 2012). "It suggests that miR-520b is able to downregulate the expression of MEKK2 and cyclin D1 in the tumor cells." (PMID 22319632, 2012). "Cases with >10% of tumor cells showing positive nuclear staining were scored for CCND1 overexpression." (PMID 22761904, 2012). "Cyclin D1 and p21 expressions were significantly increased in tumor tissues compared with normal mammary gland tissues." (PMID 23508728, 2012). "BRAF-wild-type clones present in primary tumours and metastases are likely to contain mutations or copy number alterations affecting genes other than BRAF, such as NRAS, KIT, cyclin D1, PTEN and CDKN2A." (PMID 21224857, 2011). "Another important finding of the present study was that aneuploid tumours and those with higher S phase fraction showed significantly higher frequency of cyclin D1 immunoreactivity as compared to diploid tumours and with lower S phase fraction." (PMID 21537090, 2011). "At the same time, membrane and nuclear EGFR expression in CRC, according to our knowledge, has not been published so far, and the present study was conducted with the aim to explore the correlation between mEGFR, nEGFR and cyclin-D1 expression on tumor cells." (PMID 22050898, 2011). "While Doxil itself had negligible effect on the expression of c-Myc, cyclin D1, or survivin, sFZD7 alone or in combination with Doxil decreased the tumor levels of these three downstream target proteins of Wnt/β-catenin signaling." (PMID 21314951, 2011). "This yields the interesting observation that ER-positive tumours with low cyclin D1 appear to behave similarly to ER-negative tumours with regards to their relationship to EMT markers and the claudin-low subtype." (PMID 21955753, 2011). "For instance, IKKα phosphorylates important molecules of signalling cascades (β-catenin, estrogen receptor-α transcriptional factor) which through induction of cyclin D1 and/or c-Myc expression enhances tumor proliferation." (PMID 21755017, 2011). "In stage I cyclin D1 was positive in all 17 tumor specimen (100%), in stage II in 4 from 8 (50%), in stage III 14 from 16 (87.5%) and in stage IV in 4 from 6 (66.7%)." (PMID 22024187, 2011). "Curcumin treatment inhibited cyclin D1 expression in the tumor xenografts suggesting that it inhibits cancer cell proliferation." (PMID 21347286, 2011). "Maderosian and colleagues showed that rapamycin regulates cyclin D1 and c-Myc mRNA in different types of tumor cells involving an enhancement of TTP binding activity." (PMID 21208419, 2011). "We used the immunochemistry method to investigate the expression of galectin-3 and cyclin D1 in the paraffin-embedded tumor tissue of 47 patients (32 men and 15 women; mean age 59.34 ± 8.90)." (PMID 22024187, 2011). "In contrast, cyclin D1 and c-Myc appeared to be overexpressed in almost all HCCs compared to non-tumor controls." (PMID 22132221, 2011). "The CCND1/CDKN2A ratios of all the normal tissues were significantly higher compared with those of corresponding tumor tissues, indicating that the RB1 status of all the normal tissues was positive." (PMID 21447152, 2011).
tumor (continued). "The tumor suppressor function of CYLD in skin is due to the reduced proliferation rate mainly through a delay in the G1 to S phase transition by reducing cyclin D1 expression levels in a NF-κB dependent signaling pathway." (PMID 21573132, 2011). "We also determined total β-catenin levels, the phosphorylation status of β-catenin, and CYCLIN-D1 levels prior to performing the tumor implantation experiment." (PMID 21569306, 2011). "Higher expression of cyclin D1 was observed only in 30 (66.6%) of 45 cases that correlated with advanced age (P <0.02), higher tumour stage ((P<0.01), histological differentiation and lymph node metastasis (P <0.01)." (PMID 21537090, 2011). "Analysis of nuclear DNA pattern revealed cyclin D1 immunoreactivity in tumours with aggressive DNA pattern such as aneuploidy ((P<0.05) and higher S phase fraction ((P<0.04)." (PMID 21537090, 2011). "CYCLIN-D1 is a key regulator of cell cycle progression, the increased expression of which is a fundamental characteristic of tumor cell proliferation." (PMID 21569306, 2011). "Based on its role in various pathways including ERK1/2 activation, β-catenin signalling and c-Myc/cyclin D1 expression, previous studies have suggested a putative role of GSK3β as a tumor suppressor." (PMID 22111880, 2011). "The marker genes Myc, Glul and Oat presented pre-tumor-specific differential expression which was reverted in the tumor state, whereas Ccnd1, Gpc3, Mvk, Pparg, Rbl2, Robo1 were only upregulated in tumors." (PMID 21464922, 2011). "On the other hand, the presence of CCND1 and EGFR numerical aberrations of the primary tumour was significantly associated with the presence of ECS in metastatic lymph nodes (P=0.011 and 0.004, respectively)." (PMID 21304522, 2011). "In contrast, our data show the ability of LPP3 to potentiate tumor growth by amplifying β-catenin and CYCLIN-D1 activities." (PMID 21569306, 2011). "Mishina and al. showed that the 5-year survival was better in patients with cyclin D1 positive tumours (89% vs 64%), and cyclin D1 expression tended to be a favourable prognostic factor in univariate analysis (p = 0.08)." (PMID 22024187, 2011). "As ER-negative tumours are consistently cyclin D1 low, these are less representative our in vitro experiments." (PMID 21955753, 2011). "When analyzed in relation to cell cycle parameters, significantly higher ((P<0.05) frequency of patients (80.0%) with aneuploid tumour showed cyclin D1 immunoreactivity as compared to those with diploid tumours (50%)." (PMID 21537090, 2011). "The aim of the present study was to explore and correlate membrane and nuclear EGFR and cyclin-D1 protein expression with EGFR gene status of tumor cells." (PMID 22050898, 2011). "This study documented significantly higher frequency of overexpression of cyclin D1 in patients with advanced age, advanced tumours stage and lymph node metastasis." (PMID 21537087, 2011). "Nuclear Msx2 correlated with low-grade tumours (P = 0.015), estrogen receptor positivity (P = 0.038), low Ki67 (P = 0.005) and high cyclin D1 expression (P = 0.037)." (PMID 20682066, 2010). "Cyclin D1 is a well-known oncogene whose overexpression is found in many cancers and is related to tumor progression and metastasis." (PMID 20092659, 2010). "Of these genes, the imprinted gene decorin and the oncogene EGFR were down-regulated in tumor tissues as compared to normal mammary gland tissues, and the oncogene cyclin D1 was up-regulated in tumor tissues." (PMID 20092659, 2010). "Therefore, we hypothesised that the genome status of CCND1 in primary oesophageal cancer could be predictable by a less invasive, blood-based test, which enable to evaluate primary tumour dynamics and predict prognosis and associated clinicopathological factors." (PMID 20389301, 2010).
tumor (continued). "Immunostaining of the tumor tissues showed that samples from MTA treated mice had lower levels of cyclin D1 expression that closely correlated with a lower tumor proliferation index according to the Ki67 immunostaining." (PMID 20529342, 2010). "The imprinted gene decorin and the oncogene EGFR were down-regulated in tumor tissues, while the oncogene cyclin D1 was up-regulated." (PMID 20092659, 2010). "We previously reported that DIF-1 showed anti-tumor activity by inhibiting cyclin D1 expression and the Wnt/β-catenin signaling pathway." (PMID 20843378, 2010). "Recent studies show that NGX6 gene can reduce tumor formation and tumor size in nude mice by down-regulating the EGFR/K-ras/JNK/c-Jun/cyclin D1 and Wnt/beta-catenin/TCF/LEF signal pathways." (PMID 20423473, 2010). "P16INK4A is a critical member of the Rb tumor-suppressor pathway which acts to arrest the cell-cycle at G1/S by inhibiting the binding of cdk4/6 to Cyclin D1 and subsequently inhibiting the phosphorylation of Rb." (PMID 20604950, 2010). "Chromosomal translocations, gene amplification and disruption of normal intercellular trafficking and proteolysis are the procedures which lead to accumulation of cyclin D1 in tumor cell nuclei and eventually to cyclin D1 overexpression in many tumours." (PMID 21176227, 2010). "Previously, we reported that DIFs inhibited the Wnt/β-catenin signaling pathway via glycogen synthase kinase-3β (GSK-3β) activation, leading to cell cycle arrest at G0/G1 phase through suppression of cyclin D1 expression in various human tumor cells." (PMID 20843378, 2010). "The aim of this study was to investigate the clinical relevance of BRAF V600E mutation status, cyclin D1 expression and MSI status of primary tumours of patients with mCRC treated with front-line 5FU-based chemotherapy." (PMID 20485284, 2010). "Primary tumours from 144 patients treated for mCRC were assessed for BRAF (V600E) mutation, MSI status and cyclin D1." (PMID 20485284, 2010). "We next examined the effects of resveratrol and/or TRAIL on the expression of p27/KIP1 and cyclin D1 in tumor tissues by Western blotting and immunohistochemistry." (PMID 21209944, 2010). "The detection of BRAF mutations was also correlated with cyclin D1 expression as cyclin D1 overexpression was detected in 58 and 14% of BRAF mutated and wt tumours respectively (P=0.001)." (PMID 20485284, 2010). "Nuclear Msx2 expression was associated with low-grade (P = 0.015), ER-positive (P = 0.038) tumours, low Ki67 expression (P = 0.005), and increased nuclear cyclin D1 expression (P = 0.037)." (PMID 20682066, 2010). "Immunohistochemistry (IHC) staining for cyclin D1 and Ki67 was performed on available pre- and post treatment tumor samples." (PMID 21206909, 2010). "In this way, both high expression of cyclin D1 and deregulated expression of cyclin E1 cooperate to increase tumour fitness." (PMID 21176227, 2010). "CCND1 amplification as a compact HSR was detected in the primary tumor, its recurrence and penile metastasis (after 17 and 30 months, respectively)." (PMID 20540739, 2010). "A high-dose of Celecoxib (100 mg/kg) significantly inhibited tumor growth (P < 0.05), and the expression of cyclin D1 was reduced by 61%." (PMID 21152316, 2010). "Cases were reviewed and analyzed for the immunohistochemical expression of PCNA, Ki67, p27, p16, p57, p21, cyclin-D1 and c-myc and correlated to clinico-biological endpoints of tumor size, node status, stage of the disease, and disease free survival (DFS)." (PMID 20152033, 2010).
tumor (continued). "CDKN2A (also known as p16-INK4A) is a tumor suppressor that binds to the complex of cyclin D1 and cyclin-dependent kinase 4 to repress its ability to phosphorylate the retinoblastoma protein, and consequently, blocks cell cycle progression from G1 to S." (PMID 20465802, 2010). "These two forms of cyclin D1 share a strict nuclear localization suggesting that nuclear functions of cyclin D1 are necessary and/or sufficient for tumor formation." (PMID 20459741, 2010). "In our RT-PCR study, cyclin D1 gene was up-regulated in 7/12 (58%) tumours studied, which is higher than previously reported (5–20%)." (PMID 19615042, 2009). "Cyclin D1 expression is also 3-fold higher in increase in the tumor tissues compared to normal kidney tissues." (PMID 19265534, 2009). "By real-time PCR, the expression levels of LEF-1 downstream effector genes cyclin D1 and c-myc were higher in peritumor cells compared to that of the tumor cells." (PMID 19402906, 2009). "The expression of cyclin D1 has previously been shown to positively correlate with ER status and negatively with tumour grade and size, thus suggesting that cyclin D1 overexpression is a marker of good outcome particularly when ER is coexpressed." (PMID 19615042, 2009). "Cyclin D1 expression is significantly increased up to 3-fold in tumor tissues compared to control tissue indicating that tuberin is upstream of cyclin D1." (PMID 19265534, 2009). "We therefore tested if the DR-1 and D1-1 peptide-stimulated CD3 T cells were cytotoxic to tumor cells highly expressing cyclin D1." (PMID 19707583, 2009). "Specifically, the expression levels of HBsAg, LEF-1, cyclin D1 and c-myc were studied in tumor cells and peritumor cells from the same patient." (PMID 19402906, 2009). "The impact of PEG-LPrA2 treatment on proliferation markers (PCNA and cyclin D1) was further investigated in tumor lysates by western blot analysis." (PMID 19531256, 2009). "It has been also reported that STAT5 phosphorylation regulates the expression of cyclin D1 in tumor cells including those of prostate." (PMID 19242540, 2009). "Inline with the in vitro data, analysis of tumor specimen taken from RCC patients revealed a correlation between cyclin D1 and cyclin E protein level and the tumor proliferation index." (PMID 19473483, 2009). "Cyclin A gene expression was increased in 9/12 tumours, cyclin B1 in 9/12 tumours, cyclin D1 in 7/12 tumours and cyclin E in all 12 tumours." (PMID 19615042, 2009). "More importantly, the peptide DR-1 can induce cytotoxicity of CD4 T cells against tumor cells highly expressing cyclin D1 in the context of HLA-DR.B1 molecules." (PMID 19707583, 2009). "Cyclin D1 has previously been shown to be a major mediator of ErbB2-induced tumor cell proliferation and oncogenesis." (PMID 19754954, 2009). "Overall, the in vitro and in vivo results both suggest that auraptene was effective in delaying the progression of tumor possibly through suppression of cyclin D1 protein expression." (PMID 19640308, 2009). "Results showed that compared to that of normal livers, the expression of cyclin D1 and c-myc was increased significantly in both tumor cells and peritumor cells of HCC tissues." (PMID 19402906, 2009). "Exposure to reg4 antibody resulted in a significant decrease in intra-tumor levels of pAkt, Bcl-xL, Bcl-2, survivin and cyclin D1." (PMID 19834624, 2009). "When immunostained with anti-c-Myc, cyclin D1, and survivin antibodies, tumor tissues that had been treated with anti-Wnt-1 antibody showed reduced c-Myc, cyclin D1, and survivin expressions." (PMID 19778454, 2009). "Forth, miR-503 suppresses tumor cell growth, consistent with the notion that suppression of CCND1 would inhibit cell growth." (PMID 19538740, 2009). "Of the 10 tumours with nuclear CTNNB1, eight (80%) displayed CCND1 overexpression, which included all tumours with high CTNNB1 nuclear positivity." (PMID 19293793, 2009).